TNF (tumor necrosis factor)
Diseases named in the same sentence as TNF in open-access papers (continued):
Sharing a sentence is not in itself a finding about the gene and the disease.
demyelinating disease (continued). "Two patients did not receive anti-TNFα therapy because brain MRIs at baseline revealed lesions compatible with demyelinating diseases." (PMID 24938855, 2014). "In addition, it is known that anti-TNF therapy is not appropriate in a patient who has a demyelinating disease (e.g., optic neuritis or multiple sclerosis) because such treatment can worsen outcomes." (PMID 35160280, 2022). "However, two patients, a 35-year-old man with AS and a 46-year-old woman with PsA, did not receive anti-TNFα therapy because brain MRI revealed lesions compatible with or suggestive of demyelinating disease." (PMID 24938855, 2014). "On the other hand, if these two patients had been treated with TNFα antagonists without having MRI at baseline, they might have developed symptoms and signs of demyelinating disease, but equally they may not have." (PMID 24938855, 2014). "As the capacity for TNFα therapy to neutralize CNS TNFα was not directly examined, these data may imply that peripheral TNFα is somehow required for maintaining demyelinating disease quiescence." (PMID 21812954, 2011). "Leukemia inhibitory factor (LIF) not only acts as a neurotrophic factor in CNS but also inhibits the production of oxygen radicals and TNF-α, and stimulates myelin uptake by macrophages, suggesting that LIF may be useful for treating CNS trauma or other demyelinating diseases." (PMID 20186338, 2010).
lupus nephritis (74 papers, 2009 to 2025). Glomerulonephritis in the context of systemic lupus erythematosus. "We observed that heterozygous (GA) and minor allele ‘A’ of TNF-α (G-238A) polymorphism were significantly associated with lupus nephritis." (PMID 31409832, 2019). "The beneficial role of TNF-α in the pathogenesis of disease is substantiated by findings that decreased synthesis of TNF-α in NZB/W mice is associated with the development of lupus nephritis." (PMID 24171032, 2013). "As of 2017, a study conducted on SLE by a group of researchers confirmed that tumor necrosis factor (TNF)-like weak inducer of apoptosis could activate type I IFN in lupus nephritis (LN) causing kidney injury." (PMID 34906241, 2021). "It is possible that genetic predisposition may regulate the effect of TNF-α in the pathogenesis of lupus nephritis." (PMID 24171032, 2013). "However, anti TNFα can contribute to renal injury and may directly cause glomerulonephritis or lupus nephritis." (PMID 31820145, 2021). "And following treatment with hUC-MSCs, a reduction in serum TNF-α concentrations was also observed in the five lupus nephritis patients who responded well to the treatment (patients 1 to 5)." (PMID 39557841, 2024). "Recent studies have shown that miR-155 can affect the progression of Lupus Nephritis via regulating TNF-a." (PMID 38699702, 2024). "Recent studies have shown that miR-155 can affect the progression of Lupus Nephritis via regulating TNF-α." (PMID 38699702, 2024). "NEU1 is also responsible for coordinating inflammatory responses in lupus glomerulonephritis, such as the release of tumor necrosis factor-α (TNF-α) and interleukin-6 (IL-6)." (PMID 39194692, 2024). "All forms of lupus nephritis were discovered to have high levels of TNF-α in the glomeruli, and the expression of TNF-α was linked with renal inflammatory activity." (PMID 37833861, 2023). "At the same time, quercetin can protect the kidney by reducing the level of proteinuria and the expression of interleukin-6 (IL-6) and tumor necrosis factor-α (TNF-α) in lupus nephritis (LN) mice." (PMID 37026113, 2023). "During disease progression of lupus nephritis, a higher expression of inhibitory receptor PD-1 was associated with a lower degree of CD4+ Tmem-cell functionality regarding IL-2, TNF-α and IFN-γ expression." (PMID 32441253, 2020). "The frequencies of TNF-α+ Tmem cells within the IFN-γ+ PD-1+ CD4+ subpopulations were reduced with lupus nephritis, similar to CD8+ Tmem cells in chronic infections." (PMID 32441253, 2020). "T-96 has been shown to improve lupus nephritis in mice by inhibiting the activation of NF-κB and reducing downstream pro-inflammatory mediators, such as TNF-α, COX-2 and ICAM-130." (PMID 30305611, 2018). "To date, there are few studies on necroptosis in SLE, but extensive studies on TNF-like weak inducer of apoptosis (TWEAK) have indicated a central role for the TNF pathway in the induction of lupus nephritis." (PMID 28035990, 2016). "Lupus nephritis group had significantly higher levels of TNF-α and IL-1β compared to healthy controls (5.967 ± 2.402 ng/ml vs. 5.098 ± 1.072 ng/ml, P = 0.023; 6.213 ± 2.807 ng/ml vs. 4.441 ± 1.381 ng/ml, P = 0.001, respectively)." (PMID 26817892, 2016). "In another mouse model of lupus BXSB, dihydroartemisinin was found to significantly improve lupus nephritis, reduce serum TNFα level, and suppress TNFα production from peritoneal macrophages." (PMID 25960615, 2015). "High levels of TNF-α have been demonstrated in patients with lupus nephritis, and TNF-α is overexpressed in renal tissue in lupus nephritis." (PMID 24187561, 2013). "Experimental studies have suggested that TNF-α can inhibit type I IFN, a family of pro-inflammatory cytokines known to exert pathogenic roles in the development of lupus nephritis." (PMID 24171032, 2013). "Renal expression and circulating levels of bioactive TNF-α are increased during clinical and experimental lupus nephritis and correlate with disease activity." (PMID 24171032, 2013).
lupus nephritis (continued). "Expression of IL-6, TNF-α, type I IFNs, and hyaluronan are increased in the kidneys of patients and mice with active lupus nephritis and have been shown to contribute to disease pathogenesis." (PMID 24171032, 2013). "Further analysis of inflammatory markers revealed that SAP treatment notably decreased systemic and local inflammatory cytokine levels of TNF-α, IL-1β, IL-6, IL-12, and MCP-1, which were closely associated with the severity of lupus nephritis." (PMID 21799927, 2011). "In 2010, emerging clinical data suggest a potential benefit of TNF antagonism in lupus nephritis and Wegener's granulomatosis." (PMID 20953353, 2010). "The role of TNF-α in lupus nephritis is supported by the evidence of the increased expression of TNF-α in the glomeruli; high urinary levels; and the activation of the complement cascade with and without specific TNF gene polymorphisms in the affected patients." (PMID 40507454, 2025). "Likewise, increased serum levels of TNF-α in SLE patients correlate with disease activity and are linked to systemic manifestations, including cardiovascular disease and lupus nephritis." (PMID 39335602, 2024). "As a consequence, TNF-α blockade could pose long-term danger in patients with lupus nephritis and symptoms can recur after cessation of anti-TNF-α therapy." (PMID 33861790, 2021). "Lupus nephritis is dependent on both TNF and EGFR signaling." (PMID 32911849, 2020). "GA genotype and minor allele (A) of TNF-α (G-238A) polymorphism was more frequent in patients with lupus nephritis (LN+) compared to those patients without renal involvement (LN−) (GA: P = 0.002, OR = 2.89;A: P < 0.001, OR = 2.92)." (PMID 31409832, 2019). "Thus, we further detected serum levels of TNF-α and IL-1β in active lupus nephritis patients and normal controls." (PMID 26817892, 2016). "Moreover, in patients with lupus nephritis, a significant correlation was found between serum TNF-α concentration and serum PTX3 level (r = 0.351, P = 0.012), but not between IL-1β and PTX3 (r = 0.062, P = 0.861)." (PMID 26817892, 2016). "The M1-like macrophage subtype has long been believed to be a source of pathology in lupus nephritis and the high levels of IL-6, IFN-ɣ and TNF-α found in patients with lupus nephritis support the important role of pro-inflammatory M1-like macrophages in the pathogenesis of the disease." (PMID 27091114, 2016). "Possible roles of TNF-α in the pathogenesis of lupus nephritis have been reviewed." (PMID 26441980, 2015). "TNF-α mediates inflammation and renal tissue destruction in lupus nephritis patients." (PMID 25548434, 2014). "Blockade of TNF-α activity in patients or animals with lupus nephritis may be beneficial or otherwise depending on the dose, treatment duration, and status of disease when treatment is administered." (PMID 24171032, 2013). "TNF blocking therapy may enable long‐term remission in lupus nephritis patients." (PMID 37771913, 2023). "Besides, oral artesunate (150 mg/kg/d) has demonstrated stronger protective effects than prednisone in experimental lupus nephritis, by lowering serum levels of TNF-α and IL-6, and NF-κB p65 subunit and transforming growth factor beta 1 (TGF-1β) expressions in renal tissues." (PMID 32679734, 2020). "Indeed, the inflammatory cytokines TNF (tumor necrosis factor), Interleukin-6, and BAFF (B-cell activating factor) are associated with B-cell kidney infiltration and have been shown to contribute to disease pathogenesis in patients with lupus nephritis." (PMID 26225955, 2015). "Given the observations of high serum TNF-α in active SLE and lupus nephritis, the TNF-α antagonist is still a promising therapy option for active SLE." (PMID 38069267, 2023). "DHA can similarly inhibit the secretion of TNF-α in BXSB mice and improve the pathological damage of lupus nephritis." (PMID 34483908, 2021). "For the early focal form of lupus nephritis (class III) we demonstrated a selective accumulation of slanMo, which locally expressed TNF-α." (PMID 31191513, 2019).
lupus nephritis (continued). "Serum IL-6, IL-12, TNF-α and IFN-γ levels of lupus nephritis mice treated with polysaccharide of large yellow croaker swim bladder (PLYCSB)." (PMID 24667130, 2014). "In particular, the expressions of TNF-α, IL-6 and IL-10 are markedly elevated in SLE patients with lupus nephritis." (PMID 24629023, 2014). "In this review, we provide an overview of the synthesis and putative roles of IL-6, TNF-α, IFN-α, and hyaluronan in the pathogenesis of lupus nephritis focusing on their effects on human mesangial cells and proximal renal tubular epithelial cells." (PMID 24171032, 2013). "Serum levels of IL-6, TNF-α, IFN-α, and hyaluronan (HA) are increased in patients with lupus nephritis." (PMID 24171032, 2013). "Moreover, when TNF was administered early to NZB/White (NZB/W) mice, the onset of lupus nephritis and autoantibodies was delayed." (PMID 37833861, 2023). "Furthermore, RHBDF2 activates tumor necrosis factor (TNF)‐α, and epidermal growth factor receptor (EGFR) signaling and enhances lupus nephritis." (PMID 36943228, 2023). "Deficiency of TNF, TNFR1, TNFR2, or both TNFR1&2 did not precipitate lupus nephritis in either male or female Sle1 mice as manifested by absence of proteinuria >30 mg/dL and/or premature mortality in mice aged to >1 year." (PMID 35104241, 2022). "Accumulative studies showed that tumor necrosis factor (TNF)-like weak inducer of apoptosis (TWEAK) was up-regulated in the blood and urine from patients diagnosed with lupus nephritis (LN) and that it might be used as a novel biomarker for active LN." (PMID 33307926, 2021). "Apart from a single case report of an adult patient who developed lupus nephritis after using golimumab (a new anti TNFα), there is no data on the renal effects of golimumab." (PMID 31820145, 2021). "In kidney glomerulus (Glom) and tubulointerstiitum (TI) from SLE patients with Class III/IV lupus nephritis (LN), there was no significant TNF enrichment but the other five signatures were significantly enriched in SLE patients (p < .05)." (PMID 31044165, 2019). "Proinflammatory chemokines (MCP-1) and cytokines (IL-6, TNF-α), Th1 cytokines (IL-2, IFN-γ), Th2 cytokines (IL-4, IL-10), and Th17 cytokines (IL-17A) are involved in pathogenesis of lupus nephritis, and are therapeutic targets for lupus nephritis." (PMID 27846813, 2016). "Induction of TNF-α expression in the kidney and cultured proximal renal tubular epithelial cells is mediated in part, through prior activation of p38 MAPK during progressive lupus nephritis." (PMID 24171032, 2013). "Both TNFα and INFγ were found to be up-regulated in the murine kidneys during progression of lupus nephritis when analyzing all mice in all groups (data not shown), as previously demonstrated by others." (PMID 22479529, 2012). "Furthermore, C3-LHF1 potentiated tumor necrosis factor (TNF)-induced C-X-C motif chemokine ligand 10 (CXCL10) secretion and decreased markers of healthy podocytes, suggesting a role in podocyte injury and inflammatory tissue remodeling characteristic of lupus nephritis." (PMID 41249507, 2025). "In this study, antroquinonol, the major active component of ACE, inhibited the production of TNF-α and IL-1β in LPS-induced RAW 264.7 cells, suggesting that this anti-inflammatory activity may contribute to the function of ACE in attenuation of the progression of lupus nephritis." (PMID 18955361, 2011).
inflammatory skin disease (73 papers, 2012 to 2026). Inflammatory skin disorders covers a broad category that includes many conditions ranging in severity, from mild itching to grave medical health complications These disorders are common in people of all ages and races. "Excessive production of TNF-α has been shown to induce various inflammatory events in keratinocytes associated with the pathogenesis of inflammatory skin diseases." (PMID 41465292, 2025). "HS is also an inflammatory skin disease implicated by the pathogenesis of neutrophilic inflammation, dysbiosis, TNF, interferon responses, hair- and skin-gland abnormalities, autoantibodies, and plasma cells." (PMID 38014119, 2023). "Our data warrant future studies of the regulatory mechanism controlling the development of skin disease upon cFLIP deficiency and the role of cFLIP/TNF in a number of inflammatory skin diseases, including toxic epidermal necrolysis (TEN)." (PMID 33238518, 2020). "In addition, mice with an arrested canonical NF-κB activation pathway in the keratinocytes develop a severe inflammatory skin disease shortly after birth, which is caused by TNFα- and macrophage-mediated, but T-cell–independent, mechanisms." (PMID 24802997, 2014). "Therefore, it is important to focus further research on new therapeutic approaches, developing the next generation of therapies against TNF-α for longer-term use, hopefully free from the risk of side effects in patients with acute and chronic skin inflammatory diseases." (PMID 39063004, 2024). "TNF-α plays a central role in the pathogenesis of inflammatory skin disorders by activating endothelial and dermal cells, thereby upregulating downstream mediators such as IL-6 and MMP-9." (PMID 41404493, 2025). "Environmental factors, such as ultraviolet (UV) radiation, trigger TNF-α, which is closely related to aging and inflammatory skin diseases." (PMID 40364386, 2025). "Since the treatment of mouse skin with IAP and caspase inhibitors can induce TNF-α-dependent skin inflammatory diseases, we further analysed the effect of EGF on this model system." (PMID 38789573, 2024). "COX-2, TNF-α and p-NFκB are considered to be a main target in inflammatory skin disorders and are mostly utilized in pharmacological therapy." (PMID 38778384, 2024). "Patients with inflammatory skin diseases exhibit elevated levels of tumor necrosis factor α (TNFα) and interferon γ (IFNγ) in their serum." (PMID 39274912, 2024). "HaCaT keratinocyte cells stimulated with TNF-α/IFN-γ are a commonly used in vitro model for studying inflammatory skin diseases." (PMID 38786617, 2024). "In another study on the effects of topical DP treatment on inflammatory skin disease, DP treatment reduced lesion size and mRNA expression levels of the inflammatory cytokines, TNF-α, IL-6, and IL-8." (PMID 36641447, 2023). "UVB radiation can induce inflammatory mediators such as COX-2 and pro-inflammatory cytokines, including TNF-α, IL-6, and IL-1β, which induce the expression of NF-κB, which has been shown in inflammatory skin diseases." (PMID 38275645, 2023). "Biologics, including TNFα-inhibitors, have shown good efficacy and safety in various inflammatory skin diseases." (PMID 37686161, 2023). "Together, our data suggest that there are several available therapeutic targets among the common mechanisms up-regulated in these four lesional inflammatory skin diseases, including the IL-12 complex, TNF, IFN, and the IL-23 complex." (PMID 35486723, 2022). "Intriguingly, the anti-inflammatory drugs cyclosporine, tacrolimus and dexamethasone (which are all used to treat inflammatory skin diseases) significantly inhibited TNF-induced TRPA1 upregulation." (PMID 33805042, 2021). "Despite the probably different mechanisms driving cell death induction versus inflammatory skin disease in these mouse models, TNF signaling was shown to be only partially involved in this process." (PMID 33238518, 2020).